C21orf91 (chromosome 21 open reading frame 91)
Description:
Plays a role in cortical progenitor cell proliferation and differentiation. Promotes dendritic spine development of post-migratory cortical projection neurons by modulating the beta-catenin signaling pathway.
Synonyms: EURL; C21orf14; C21orf38; YG81; CSSG1; BTG3-7:1
Tractability: PROTAC: ubiquitination databases record sites on it.
Gene: Protein-coding gene on chromosome 21 (17,788,974 to 17,819,386, reverse strand). Ensembl gene ENSG00000154642.
Subcellular location (Human Protein Atlas): Microtubules; Cytokinetic bridge
Gene Ontology:
Biological process: cerebral cortex neuron differentiation; positive regulation of dendritic spine development
Genetic constraint (gnomAD): Loss-of-function variants: 17 observed, 22.43 expected, observed/expected ratio (o/e) 0.76, 90% interval 0.52 to 1.14. The upper end of that interval is the gene's LOEUF score, 1.14, which puts it in group 4 of 6, group 1 being the genes least tolerant of losing a copy. Missense variants: 219 observed, 265.56 expected, observed/expected ratio (o/e) 0.82, 90% interval 0.74 to 0.92. Synonymous variants: 90 observed, 93.52 expected, observed/expected ratio (o/e) 0.96, 90% interval 0.81 to 1.15.
Homologues: Orthologues: chimpanzee C21H21orf91 (99% identical), macaque C3H21orf91 (98% identical), rabbit C21orf91 (92% identical), dog C21orf91 (91% identical), pig C21orf91 (89% identical), rat C11h21orf91 (83% identical), guinea pig C21orf91 (82% identical), mouse D16Ertd472e (80% identical), tropical clawed frog c2h21orf91 (66% identical), zebrafish C10H21orf91 (49% identical).
Diseases named in the same sentence as C21orf91 in open-access papers:
C21orf91 is named in the same sentence as 8 diseases in open-access papers, as found by Europe PMC text mining. Sharing a sentence is not in itself a finding about the gene and the disease. The quoted sentences say what the papers report.
breast carcinoma (1 paper, 2020). "In previous study, few results showed that C21ORF91 gene was involved in hepatocellular carcinoma cells (HCC) progress, and no report of C21ORF91 gene focus on breast cancer, especially TNBC." (PMID 33585557, 2020).
Down syndrome (1 paper, 2016). "Here, we focussed on the neurodevelopmental functions for EURL (also known as C21ORF91, Refseq Gene ID:54149), a protein-coding gene at the centromeric boundary of the Down Syndrome Critical Region (DSCR) of HSA21." (PMID 27404227, 2016).
herpes labialis (1 paper, 2019). A lesion caused by type 1 or type 2 herpes simplex virus, typically involving the oralfacial region. "The C21orf91 gene, also known as the Cold Sore Susceptibility Gene 1, is located on chromosome 21 and is associated with herpes labialis manifestation." (PMID 31757016, 2019). "Researchers have found a connection between the C21orf91 gene and herpes labialis between the gene and Down syndrome, as well as hepatocellular carcinoma." (PMID 31757016, 2019). "The ways in which the C21orf91 gene influences pathogenesis and manifestation of herpes labialis have not been established yet." (PMID 31757016, 2019).
melanoma (1 paper, 2021). A malignant, usually aggressive tumor composed of atypical, neoplastic melanocytes. "C21orf91 is therefore a critical molecule controlling proliferation of melanoma cells from at least two pathways, one of which is the canonical pigment-cell phenotype switching pathway driven by MITF." (PMID 34145395, 2021).
cancer (1 paper, 2020). A tumor composed of atypical neoplastic, often pleomorphic cells that invade other tissues. "In this study, we first screened out TNBC specific lncRNA Lnc-BTG3-7:1, which sustained tumor progress, and this TNBC specific lncRNA and its target C21ORF91 gene were involved in Wnt/β-catenin and MAPK pathways, which were associated with cancer cell progress." (PMID 33585557, 2020).
C21orf91 also shares sentences with these, for which no sentence is quoted: fetal growth restriction (1 paper); hepatocellular carcinoma (1); tumor (1).